ZSCAN32 (zinc finger and SCAN domain containing 32)
Description:
May be involved in transcriptional regulation.
Synonyms: HCCS-5; ZNF434; FLJ20417
Tractability: PROTAC: UniProt records ubiquitination sites on it; ubiquitination databases record sites on it.
Gene: Protein-coding gene on chromosome 16 (3,382,081 to 3,401,065, reverse strand). Ensembl gene ENSG00000140987.
Subcellular location: Nucleus
Subcellular location (Human Protein Atlas): Nucleoplasm; Cytosol
Pathways (Reactome):
Gene expression (Transcription): Generic Transcription Pathway
Gene Ontology:
Molecular function: identical protein binding; protein binding; DNA-binding transcription factor activity, RNA polymerase II-specific; RNA polymerase II cis-regulatory region sequence-specific DNA binding
Biological process: regulation of transcription by RNA polymerase II; regulation of DNA-templated transcription
Cellular component: nucleus
Genetic constraint (gnomAD): Loss-of-function variants: 53 observed, 47.89 expected, observed/expected ratio (o/e) 1.11, 90% interval 0.89 to 1.39. The upper end of that interval is the gene's LOEUF score, 1.39, which puts it in group 5 of 6, group 1 being the genes least tolerant of losing a copy. Missense variants: 959 observed, 866.38 expected, observed/expected ratio (o/e) 1.11, 90% interval 1.05 to 1.17. Synonymous variants: 346 observed, 309.42 expected, observed/expected ratio (o/e) 1.12, 90% interval 1.02 to 1.22.
Homologues: Orthologues: chimpanzee ZSCAN32 (99% identical), macaque ZSCAN32 (94% identical), Drosophila melanogaster CG12391 (11% identical), Drosophila melanogaster hb (9% identical), Caenorhabditis elegans hbl-1 (7% identical), Caenorhabditis elegans Y5F2A.4 (7% identical). Paralogues in human: ZKSCAN2 (45% identical), ZSCAN29 (43% identical), ZNF18 (23% identical), ZNF274 (22% identical), ZNF496 (21% identical), ZNF202 (21% identical), ZSCAN5C (18% identical), ZNF174 (18% identical), ZSCAN5A (18% identical), ZSCAN5B (17% identical), ZNF446 (17% identical), ZSCAN1 (15% identical), and 17 more.
Diseases named in the same sentence as ZSCAN32 in open-access papers:
ZSCAN32 is named in the same sentence as 3 diseases in open-access papers, as found by Europe PMC text mining. Sharing a sentence is not in itself a finding about the gene and the disease. The quoted sentences say what the papers report.
Obesity (1 paper, 2020). Accumulation of substantial excess body fat. "Based on the obtained results, the ZSCAN32, PLCD4, HOXC13, and ADCY9 from obesity predicted genes, as well as LIMA1, and SLC22A23 from CRC predicted genes were significantly related to CRC survival rate." (PMID 33073494, 2020).
ZSCAN32 also shares sentences with these, for which no sentence is quoted: depression (1 paper); lung carcinoma (1).